KLF6 (KLF transcription factor 6)
Diseases named in the same sentence as KLF6 in open-access papers (continued):
Sharing a sentence is not in itself a finding about the gene and the disease.
breast cancer (continued). "Microarray analysis comparing the populations in which the reporter construct is active versus inactive showed that positive cells expressed higher mRNA levels of cytokines (IL-8, IL-6, TNF) and genes (such as ATF3, SNAI2, and KLF6) previously related with the CSC phenotype in breast cancer." (PMID 25414831, 2014). "This hypothesis is in line with recent findings which demonstrate that cytoplasmic KLF6 is able to interact with c-Src protein and thereby to interfere with estrogen receptor alpha-mediated cell growth of breast cancer cells." (PMID 21799854, 2011). "As an essential step to gain knowledge about function of KLF6 in breast tumors, the expression pattern and sub-cellular distribution of KLF6 protein was analyzed in samples of human breast cancer along with the expression of ERBB2 as a tumor aggressiveness marker." (PMID 20126619, 2010). "In this regard, Guo and co-workers demonstrated a decreased binding of KLF6 to its DNA binding sequence on the Tissue Factor Pathway Inhibitor-2 (TFPI-2) gene due to CpG hypermethylation in highly invasive breast cancer cell lines, suggesting a tumor suppressor function of KLF6." (PMID 20126619, 2010). "Thus, in addition to its nuclear localization and its function as a transcription factor, cytoplasmic KLF6 is able to interact with c-Src protein and thereby interferes with Estrogen Receptor alpha-mediated cell growth of breast cancer cells." (PMID 20126619, 2010). "Thus, despite of the limited knowledge about the KLF6 role in breast cancer, our results strongly indicate that KLF6 is expressed in breast tumor tissues, even at higher levels than a control breast tissue." (PMID 20126619, 2010). "However, siRNA mediated knockdown of endogenous KLF6 in the MCF7 breast cancer-derived cell line lead to reduced cell proliferation." (PMID 20126619, 2010). "In addition, KLF6 knockdown in MCF7 breast cancer cells leads to a cell cycle arrest affecting the G1-S transition." (PMID 20126619, 2010). "Although is still early to fully understand the KLF6 function in tumorigenesis, results of this work suggest that the tumor suppressor function described for KLF6 could be recruited and/or subverted in the context of breast cancer environment, contributing to tumor development." (PMID 20126619, 2010). "Therefore, lncRNA Xist competes with miR-101-3p to regulate the expression of C/EBPα and KLF6 to mediate Mφs polarization, promote the expression of lncRNA Xist in M1 Mφs and inhibit the expression of miR-101-3p in M2 Mφs, thus inhibiting the progression of breast cancer." (PMID 35145526, 2022). "CpG methylation in the promoter of TFPI2 inhibits binding ability between Kruppel-like factor 6 (KLF6) and TFPI2 in breast cancer." (PMID 32248791, 2020). "Interestingly, AS of human KLF6 results in the dominant negative splice isoform KLF6-SV1, which has been identified as a key driver of breast cancer and prostate cancer metastasis by promoting cell survival, migration, and invasion." (PMID 31443305, 2019). "Alternatively, BCL6 could regulate multiple other molecules like KLF6, a direct target of BCL6 in breast cancer cells." (PMID 29312557, 2017). "The ERBB2 overexpressing ductal breast carcinomas were analyzed with respect to size, tumor stage and histological grade, presence or absence of axillary lymph node metastasis, and nuclear KLF6 immunostain." (PMID 20126619, 2010). "In addition, the mutation SM5 and SM6 decreased the promoter activity most significantly (P < 0.01) and this region contains the core matrix of KLF6, indicating that KLF6 plays an important role in the regulation of TFPI-2 in breast cancer cells." (PMID 18053161, 2007).
breast cancer (continued). "To evaluate the functional significance of the predicted shared MYC/KLF6 transcriptional targets, we examined expression data derived from a model of MYC-driven cellular transformation of quiescent human mammary epithelial cells and from MMTV-Myc-driven mammary tumors in mice." (PMID 18190704, 2008). "Following these results, it is interesting to hypothesize that some endogenous or external signals, still not known, could regulate KLF6 distribution in specific cells and in some ones, like in ductal breast cancer cells; these signals could be constitutively activated." (PMID 20126619, 2010). "However, independently of which mechanism takes place, it was recently shown that reduction or absence of KLF6 abrogates the negative control of breast cancer cell proliferation triggered by Estrogen Receptor alpha through the signaling pathway mediated by c-Src and Akt activation." (PMID 20126619, 2010).
hepatocellular carcinoma (28 papers, 2008 to 2024). A malignant tumor that arises from hepatocytes. "In several cancers including hepatocellular carcinoma, alternative splicing of the Kruppel-like factor 6 (KLF6) tumor suppressor gene leads to a pathogenic AS-NMD splice variant associated with increased tumor metastasis and mortality." (PMID 30916337, 2019). "The loss or reduction of KLF6 is linked to the progression of hepatocellular carcinoma, but its contribution to liver regeneration and repair in acute liver injury are lacking so far." (PMID 28808340, 2017). "NMD inhibition has been reported in cancer, where it leads to the stabilization of transcripts that are important for tumorigenesis, such as KLF6 (Kruppel-like factor 6) in hepatocellular carcinoma and MALAT1 (metastasis-associated lung adenocarcinoma transcript 1) in gastric cancer." (PMID 34389041, 2021). "Moreover, in agreement with a previous study in hepatocellular carcinoma, we found that loss of one KLF6 allele significantly shortens both progression-free and overall patient survival." (PMID 28166199, 2017). "Unlike the JUN gene, which is known to regulate myeloid differentiation, the KLF6 gene is a known tumor suppressor for prostate, colorectal, lung, ovary, gliomas, head and neck, and hepatocellular cancer." (PMID 37298367, 2023). "In hepatocellular carcinoma, activation of the RAS/PI3K/AKT pathway leads to the expression of KLF6 splicing variant 1 (KLF6-SV1), which antagonizes the function of full-length KLF6." (PMID 37296881, 2023). "In hepatocellular carcinoma, RAS signaling led to AKT activation and subsequent SRSF1-dependent splicing of the SV1 isoform of Krüppel-like factor 6 (KLF6), a cytoplasmic inactive variant of this tumor-suppressing transcription factor." (PMID 29286307, 2017). "In addition, we found that the SV2 variant of KLF6 is downregulated in hepatocellular carcinoma (HCC) that results in inhibition of cell proliferation and induction of apoptosis." (PMID 24378751, 2013). "Most importantly, in hepatoma cell lines the situation is particularly interesting since KLF6 knockdown led to dephosphorylation of Rb together with downregulation of Cyclin D1, which in turn strongly impaired cell proliferation involving G1-S arrest." (PMID 20126619, 2010). "In addition, KLF6 splicing variant SV2 is down-regulated in hepatocellular carcinoma (HCC) and may act as an inhibitor of cell proliferation and as a promoter of cell death by apoptosis." (PMID 24378751, 2013). "Thus, the phenotypes described in klf6−/− mice, stem cells and hepatoma cell lines suggests that endogenous KLF6 is required for cell cycle progression, thereby contrasting with its potential tumor-suppressor activity." (PMID 20126619, 2010). "KLF6 expression and function have been extensively investigated in hepatocellular carcinoma (HCC)." (PMID 20119532, 2009). "Our studies also showed that platelet-derived TGF-β-mediated KLF6 expression and induced the proliferation of hepatocellular carcinoma (HCC) cells." (PMID 30692520, 2019). "That study demonstrated the reciprocal expression of KLF6 and PTTG1 both in hepatocellular carcinoma (HCC) patient samples and in the HepG2 cell line, suggesting that the loss of KLF6 and the subsequent up-regulation of PTTG1 could contribute to tumorigenesis in HCC." (PMID 23977008, 2013). "Through further studies on mouse models and samples of hepatocellular carcinoma (HCC) patients infected with HCV, it was found that the inactivation of KLF6 and the increase of KLF6-SV1 have separate and complementary effects on tumor propensity." (PMID 33816511, 2021). "However, the role of KLF6 in hepatocellular carcinoma (HCC) remains unclear." (PMID 27057625, 2016). "Moreover, upregulation of cancer-specific isoforms of TP73, CDH17, KLF6, FGFr2, FGFR3, DNMT3b3, and OPN has been reported in human hepatocellular carcinoma (HCC) and promoted cell cycle progression, proliferation, invasion and metastasis." (PMID 35463320, 2022).
hepatocellular carcinoma (continued). "For instance, in hepatocellular carcinoma (HCC), SRSF1 can enhance KLF6 alternative splicing through the phosphoinositide 3-kinase (PI3K)/Akt signaling pathway, generating three splice variants that expedite tumor progression and metastasis." (PMID 38735973, 2024).
liver fibrosis (25 papers, 2010 to 2025). "This study unravels a novel signaling cascade involving NEAT1, miR-122, and KLF6, providing profound insights into the molecular mechanisms underlying liver fibrosis." (PMID 38511056, 2024). "On the contrary, patients with KLF6 IVS 1-27 G > A polymorphism reported lower numbers of liver fibrosis, as well as a milder form of NAFLD." (PMID 32998281, 2020). "During hepatic fibrosis, KLF6 directly associated with the TGF-β gene." (PMID 21849067, 2011). "Our previous study demonstrated that MSCs-derived exosomes exert protective effects against liver fibrosis by delivering miR-148a to macrophages, which targets the KLF6/STAT3 pathway." (PMID 40873954, 2025). "miR-148a released by MSC-ex regulates the function of intrahepatic macrophages and prevents liver fibrosis through the KLF6/STAT3 signaling pathway." (PMID 37328872, 2023). "Related mechanistic studies suggest that Kruppel-like factor 6 (KLF6), as an important pro-fibrotic gene, is involved in the regulation of liver fibrosis by NEAT1, and that NEAT1 overexpression induces KLF6 mRNA and protein expression." (PMID 34899344, 2021). "During liver fibrosis, hepatic stellate cells (which can be considered as equivalent to fibroblasts) showed induction of KLF-6 induction at the mRNA and the protein level." (PMID 23840546, 2013). "miR-148a from MSC-derived exosomes prevents liver fibrosis by targeting KLF6/STAT3 pathway." (PMID 38756248, 2024). "lncRNA NEAT1 and miR-122 interacted directly in that lncRNA NEAT1 could regulate KLF6 expression in liver fibrosis by competitively binding to miR-122, thereby accelerating HSC activation and increased cell proliferation and collagen activation." (PMID 34899344, 2021). "Increased KLF6 expression augments enhanced collagen 1 and TGFß1 expression to result in liver fibrosis, and overexpression of KLF2 induces expression of the fatty acid translocator CD36 whereas KLF15 plays an essential role in ER stress-mediated insulin resistance in the liver." (PMID 29296203, 2017). "KLF6 mediated TGF-β expression was shown to contribute to the development of hepatic fibrosis." (PMID 21849067, 2011). "Control and KLF6 silenced cells were infected with purified RSV (1 MOI), since KLF6 regulates TGF-β gene expression during hepatic fibrosis and thus, we examined whether KLF6 play a similar role during virus infection." (PMID 21849067, 2011). "Furthermore, KLF6 is upregulated during liver fibrosis, which was confirmed in an animal model of liver cirrhosis and human liver cirrhosis, and targeted KLF6 therapy has been demonstrated to inhibit advanced liver fibrosis and attenuates angioarchitectural changes that typify cirrhosis." (PMID 31189661, 2019). "Therefore, investigation of the role of KLF6 may enable the identification of the underlying mechanism of not only pulmonary angiogenesis but also intrahepatic angiogenesis and liver fibrosis, and targeted KLF6 therapy may benefit HPS patients." (PMID 31189661, 2019). "Kruppel-like factor 6 (KLF6), a member of the Kruppel-like family, was identified as an activator of several genes involved in the development of liver fibrosis, and its expression is increased during progression to fibrosis in a rat NASH model." (PMID 33716968, 2021). "It has been confirmed that BMP9 circulates at a high level in serum and promotes liver fibrosis; thus, it would be worthwhile to analyze the effect of BMP9 on the expression of KLF6 in ECs under the context of HPS." (PMID 31189661, 2019). "The expressions of KLF6 and TGFβ were found to be augmented during the progression of NAFLD to NASH, thereby corroborating the roles of the KLF6-TGFβ axis in the development and progression of liver fibrosis and steatosis." (PMID 32998281, 2020).
liver fibrosis (continued). "miR-148a targets Kruppel-like factor 6 (KLF6) to suppress pro-inflammatory macrophages and promote anti-inflammatory macrophages by inhibiting the STAT3 pathway, which could be exploited as a potential therapeutic target for liver fibrosis." (PMID 37237523, 2023).
ovarian carcinoma (20 papers, 2008 to 2024). A malignant neoplasm originating from the surface ovarian epithelium. "Previous studies showed direct evidence that loss-of-function of KLF6 or HNF1B decreased expression of EXT1 in cultured mouse bone marrow-derived macrophages or ovarian cancer cell line SKOV3." (PMID 37308486, 2023). "In ovarian cancer, it has been shown that overexpression of lncRNA Xist regulates KLF6 through competition with miR-101 expression mediates TAM polarization towards M1 macrophages, thereby inhibiting the proliferation and migration ability of OC cells." (PMID 39161779, 2024). "It has been noted that miR-200b is highly expressed in plasma-derived exosomes of ovarian cancer patients and induces macrophage M2 polarization through inhibition of KLF6 expression, promoting proliferation and invasion of ovarian cancer cells." (PMID 36439168, 2022). "For example, KLF6 can be targeted by miRNA-630 to regulate the growth and invasion in ovarian cancer." (PMID 36615000, 2022). "The hub-protein KLF6 has a direct involvement in ovarian cancer cell proliferation and metastasis promotion and also works as a critical regulator of pathogenic myeloid cell activation in human." (PMID 35277538, 2022). "Then we evaluated the effect of the KLF6 expression level on the survival of ovarian cancer patients through the TCGA OV database of the UALCAN Website." (PMID 34776953, 2021). "Overall, our data indicated that miR-200b was increased in the plasma-derived exosomes of EOC patients, and it boosted ovarian cancer cell proliferation and invasion via inducing macrophages M2 polarization by suppressing KLF6 expression." (PMID 34078414, 2021). "After evaluating the correlation between KLF6 and ovarian cancer, we obtained 20 genes co-expressed with KLF6 in ovarian cancer samples based on the TCGA mRNA expression profiles on the cBioPortal Website." (PMID 34776953, 2021). "Conclusion: lncRNA OR3A4 promotes the proliferation and metastasis of ovarian cancer through the KLF6 pathway." (PMID 34776953, 2021). "A negative prognosis has been linked to elevated levels of KLF6 expression in different forms of cancer, such as in prostate, lung, and ovarian cancer." (PMID 38305787, 2024). "Studies have pointed out that miR-200b is highly expressed in plasma-derived exosomes from patients with ovarian cancer, and it promotes the proliferation and invasion of ovarian cancer cells by inhibiting the expression of KLF6 to induce the polarization of macrophages M2." (PMID 34973152, 2022). "Overall, our results demonstrated that miR-200b was highly expressed in the plasma-derived exosome of ovarian cancer patients, and promoted the proliferation and invasion of ovarian cancer cells through inducing macrophage M2 polarization by suppressing KLF6 expression." (PMID 34078414, 2021). "Therefore, this study aims to take lncRNA OR3A4 and KLF6 as research objects and try to explore their roles in ovarian cancer cells." (PMID 34776953, 2021). "At present, lncRNA OR3A4 in the occurrence and development of ovarian cancer is difficult to identify and the role of KLF6 as a tumor suppressor in ovarian cancer is also unknown." (PMID 34776953, 2021). "At present, studies have shown that KLF6 silencing in ovarian cancer can promote cell and tumor growth and blood vessel production, but whether it can promote apoptosis of ovarian cancer has yet to be further studied." (PMID 34776953, 2021). "Followed by ovarian cancer, there was 5.14% alteration of KLF6 in 584 cases." (PMID 34776953, 2021). "Besides, increased KLF6-SV1 expression and decreased KLF6 expression seem to play an important role in the regulation of cisplatin sensitivity in ovarian cancer." (PMID 32244895, 2020). "Therefore, the role of long non-coding RNA OR3A4 and KLF6 in ovarian cancer, and whether they are related became the purpose of this study." (PMID 34776953, 2021).
ovarian carcinoma (continued). "In order to further prove the role of KLF6 in ovarian cancer, this study used siRNA technology to study the role of KLF6 in isolation-induced apoptosis of ovarian cancer cells, providing a theoretical basis for further revealing the role of KLF6 in the pathogenesis of ovarian cancer." (PMID 34776953, 2021). "The results show that in ovarian cancer, lncRNA OR3A4 can inhibit the expression of KLF6 expression and, at the same time, promote the cell migration and invasion ability, and the declined KLF6 expression can also block the apoptosis induced by cisplatin." (PMID 34776953, 2021). "In addition, EVs secreted by ovarian cancer (OC) cell lines carrying miRNAs promoted CAF activation and OC metastasis via the miR-630/KLF6/NF-κB axis." (PMID 39056778, 2024). "Hence, XIST competes with miR-101 to bind with C/EBPα and KLF6 and sponges miR-101 to upregulate the expression of C/EBPα and KLF6 in TAM of ovarian cancer and BC." (PMID 36263199, 2022). "KLF6 expression in tumors was lower in ovarian cancer than in normal ovarian epithelial cells, while its splice variant KLF6-SV1 expression was higher and correlated with advanced tumor grade." (PMID 35345512, 2022). "Among them, KLF6, a target gene related to GCC, was chosen for further study, since KLF6 functions as an important regulator controlling the occurrence and development of various tumors, including thyroid cancer, ovarian cancer and gastric cancer." (PMID 34524611, 2021). "By detecting the overexpression of long non-coding RNA OR3A4 in ovarian cancer tissues and ovarian cancer cells, this study found that the increased expression of OR3A4 could inhibit the expression of KLF6, and the knockdown of OR3A4 could inhibit the migration and invasion of ovarian cancer cells." (PMID 34776953, 2021). "In ovarian cancer, some molecules could accelerate the development of the disease through binding with the 3’-UTR region of KLF6 and then suppressing the expression of KLF6, for instance miR-630." (PMID 34078414, 2021).